DNMT3A (DNA methyltransferase 3 alpha)
Diseases named in the same sentence as DNMT3A in open-access papers (continued):
Sharing a sentence is not in itself a finding about the gene and the disease.
chronic heart failure (8 papers, 2021 to 2025). "Specifically, patients with chronic heart failure display a pro‐inflammatory gene signature in their circulating myeloid cells, which is further aggravated in carriers of DNMT3A/TET2 CHIP‐driver mutations." (PMID 40702883, 2025). "Age‐related somatic mutations in DNMT3A‐driven CHIP are significantly associated with the progression and poor prognosis of chronic heart failure." (PMID 39006763, 2024). "At least for male patients with chronic heart failure, LOY ≥17% appears to be an independent risk factor for increased mortality, and its co‐occurrence with CHIP may partly confound the prognostic significance of DNMT3A/TET2 CHIP‐driver mutations." (PMID 40702883, 2025). "Monocytes derived from chronic heart failure patients carrying DNMT3A mutations revealed a significantly increased expression of inflammasome genes, such as NLRP3 and IL-1β, compared with the monocytes isolated from chronic heart failure patients with no DNMT3A mutations." (PMID 34299198, 2021).
cutaneous melanoma (8 papers, 2016 to 2024). A primary melanoma arising from atypical melanocytes in the skin. "In cutaneous melanoma, down-regulation of miR-29c has been associated with an adverse prognosis, attributed in part to its regulation of transcripts for the DNA methyltransferases DNMT3A/DNMT3B." (PMID 27852308, 2016). "We also found that RARA-AS1 was significantly correlated with all methyltransferase genes (DNMT3B, DNMT3A, TRDMT1, and DNMT) in KIRC, LGG, Skin cutaneous melanoma (SKCM), and UVM." (PMID 37833349, 2023).
endometrial cancer (8 papers, 2009 to 2024). Primary or metastatic malignant neoplasm involving the endometrium (mucous membrane that lines the endometrial cavity). "It has been suggested that overexpression of DNMT3a and DNMT3b contribute to hypermethylation of ERα and PR, subsequently silencing these genes in endometrial cancer." (PMID 35372016, 2022). "Furthermore, two of the miRNAs were known to target DNMT3A, the gene regulating epigenetic modulation and underlying DNA MMR in sporadic endometrial carcinoma." (PMID 37958433, 2023). "Moreover, in accordance with our results, we hypothesise that ARCH-related mutations (in the DNMT3A and TET2 genes) could be associated with a worse prognosis for endometrial cancer patients." (PMID 37175518, 2023).
liver fibrosis (8 papers, 2020 to 2026). "For example, lncRNA HIF1A-AS3 affects the expression of DNMT3a through downregulation of miR-129-5; the lncRNA-SNHG7/miR-29b/DNMT3a axis affects the activation, autophagy and proliferation of hepatic stellate cells in liver fibrosis." (PMID 35077478, 2022). "DNMT3A induces a DNMT-regulated DNA ab initio methylation process, and DNA methylation/hydroxy methylation, a key step in HSC activation and liver fibrosis development, can be inhibited by activation of DNMT3A expression in HSCs." (PMID 34899344, 2021). "The lncSnhg7/miR-29b/DNMT3A axis affects activation, autophagy and proliferation of hepatic stellate cells in liver fibrosis." (PMID 35087510, 2021). "In sum, our study found that epigenetic DNMT3A silencing of ANRIL enhances liver fibrosis and HSC activation through activating AMPK pathway." (PMID 31961061, 2020). "We also have been showed that DNMT3A mediates HSC activation in liver fibrosis by down‐regulating the expression of LncRNA ANRIL." (PMID 31961061, 2020). "Here, we document DNA methylation modification and their regulatory enzyme (DNMT3A) and LncRNA ANRIL that accompany liver fibrosis and HSC activation." (PMID 31961061, 2020). "Targeting epigenetic modulators DNMT3A and ANRIL, and offer a novel approach for liver fibrosis therapy." (PMID 31961061, 2020). "Here, our study demonstrated that ANRIL was significantly decreased in activated HSC and liver fibrosis tissues, while Col1A1, α‐SMA and DNMT3A were significantly increased in activated HSC and liver fibrosis tissues." (PMID 31961061, 2020). "Our findings suggest that epigenetic DNMT3A silencing of ANRIL enhances liver fibrosis and HSC activation through activating AMPK pathway, and offer a novel approach for liver fibrosis therapy." (PMID 31961061, 2020). "DNMT3A was increased in TGF‐β1 induces activated HSC and liver fibrosis." (PMID 31961061, 2020). "The expression levels of DNA methyltransferases 3A (DNMT3A), ANRIL, α‐Smooth muscle actin (α‐SMA), Type I collagen (Col1A1), adenosine monophosphate‐activated protein kinase (AMPK) and p‐AMPK in rat and human liver fibrosis were detected by immunohistochemistry, qRT‐PCR and Western blotting." (PMID 31961061, 2020).
neuroblastoma (8 papers, 2006 to 2025). Neuroblastoma (NB) is the most common solid, extracranial childhood tumor. "Despite efforts by the PCGP and other pediatric cancer genomics initiatives, many uncommon pediatric tumors require improved genomic characterization, and three-platform sequencing generates candidates for functional follow-up (e.g. DNMT3A in neuroblastoma)." (PMID 30262806, 2018). "A recent study in murine neuroblastoma cells demonstrates that over-expression of dnmt3a and -b by transfection leads to cisplatin resistance, which can be reverted by treating these cells with 5-azacytidine." (PMID 16893460, 2006). "PI3Kα inhibitor PIK-75 (78.9% cytotoxicity) stimulates anti-neuroblastoma activity by destabilizing MYCN and sensitizing tumor cells to anthracyclines, and indeed increased cytotoxicity with PIK-75 was associated with PPM1D and GNA13 gain, and DNMT3A, CBL, EED and ASXL2 loss." (PMID 34722256, 2021). "Although DNMT3A is a known driver gene in AML37, the significance of this finding in neuroblastoma is uncertain at present." (PMID 30262806, 2018). "The first was a 50 kb somatic deletion detected by WGS CNA analysis but not by WES within DNMT3A in neuroblastoma SJNBL030014." (PMID 30262806, 2018). "Moreover, four genes from the methionine metabolism gene set, such, AHCY, CBS, DNMT3A, and MTAP, are markers of poor prognosis for neuroblastoma and breast, but not for colon and lung, cancer patients." (PMID 36361596, 2022).
osteosarcoma (8 papers, 2010 to 2024). A usually aggressive malignant bone-forming mesenchymal neoplasm, predominantly affecting adolescents and young adults. "Conversely, a decrease of HDAC2 or DNMT3a expression or loss of both inhibits the formation of HDAC2/DNMT3a complex leading to transcription of genes involved in osteosarcoma stemness." (PMID 30509303, 2018). "In another noteworthy paper, the deletion of the DNA methyltransferase 3 alpha (DNMT3A) in EphA2-CAR T-cells rendered these cells more potent against locoregional osteosarcoma." (PMID 39317919, 2024). "Aberrant regulation of DNMT3A is important to the tumorigenesis of multiple cancers, which was also confirmed in osteosarcoma." (PMID 36059626, 2022). "In osteosarcoma, DNMT3A promotes APCDD1 promoter DNA hyper-methylation, downregulates its expression, and promotes cell invasion and metastasis." (PMID 36059626, 2022). "Mechanism studies revealed that circ0038632 sponged miR-186 to upregulate the expression of DNA methyltransferase 3A (DNMT3A) to promote osteosarcoma progression." (PMID 36059626, 2022). "In conclusion, we showed that the circ0038632/miR-186/DNMT3A axis was involved in osteosarcoma proliferation and metastasis." (PMID 36059626, 2022). "Next, DNMT3A expression was checked in osteosarcoma cells and tissues, and we found it had a noticeable raised trend." (PMID 36059626, 2022). "Then, we identify for the first time two enzymes, HDAC2 and DNMT3a, that have a key role in maintaining stemness status of osteosarcoma cells sustaining also the tumor growth in vivo." (PMID 30509303, 2018). "Collectively, these results support a model by which the modulation of HDAC2 and DNMT3a plays a key role in generating and maintaining the cancer stem phenotype in osteosarcoma." (PMID 30509303, 2018). "Unfortunately, a silencing also for DNMT3a cannot be performed because it highly prevents osteosarcoma cells viability." (PMID 30509303, 2018). "For example, Myc repression of p21Waf1/CIP1 transcription in human U2OS osteosarcoma cells occurs via formation of a repressive complex including Myc, Miz1 and DNA Methyltransferase3a (Dnmt3a)." (PMID 20426839, 2010). "Here, DNMT3A expression was found to be noticeably increased in osteosarcoma." (PMID 36059626, 2022). "The circ0038632/miR-186/DNMT3A axis was involved in osteosarcoma progression." (PMID 36059626, 2022). "The process may implement by circ0038632 sponging miR-186, followed by increasing the expression of DNA methyltransferase 3A (DNMT3A), and finally promoting osteosarcoma progression." (PMID 36059626, 2022). "The results showed that DNMT3A WT 3′-UTR + miR-186 co-transfection group showed a sharp decrease relative luciferase activity in osteosarcoma, and DNMT3A WT 3′-UTR + miR-186 inhibitor co-transfection group showed an apparent increase compared with DNMT3A MUT 3′-UTR + miR-186 co-transfection group." (PMID 36059626, 2022). "HDAC2 and DNMT3a are key enzymes in generating cancer stem phenotype in osteosarcoma; iv." (PMID 30509303, 2018). "This is a very interesting finding, as it highlights that DNMT3a could be a key factor involved in cancer stemness in osteosarcoma carcinogenesis." (PMID 30509303, 2018). "Moreover, miR-186 was conductive to the inhibition of DNMT3A expression, and miR-186 inhibitor reversed DNMT3A expression, revealing the expression that its target gene DNMT3A could be regulated by miR-186 in osteosarcoma." (PMID 36059626, 2022). "Subsequent RIP assay results demonstrated that circ0038632, DNMT3A, and miR-186 enrichment was majorly raised in anti-AGO2 group in osteosarcoma cells." (PMID 36059626, 2022). "Moreover, inhibition of circ0038632 decreased the expression of DNMT3A, but miR-186 inhibitor could rescue the decrease, revealing that circ0038632 could sponge miR-186 and regulate the expression of DNMT3A in osteosarcoma." (PMID 36059626, 2022).
osteosarcoma (continued). "Prompted by the evidence that 1 decreased DNMT expression in primary osteosarcoma cells, and 4 phenocopied similar effects in HCT116 and PC-3 cells, we tested selected compounds 2b and 4c as representative samples of the 2 and 4 series to study their effects on DNMT1 and DNMT3A protein expression." (PMID 32075099, 2020).
type 2 diabetes (8 papers, 2013 to 2025). "Remarkably, a recent study reported a potential protective association of CHIP with DNMT3A mutation with diabetic polyneuropathy in patients with type 2 diabetes, whereas TET2 mutation showed a positive association." (PMID 36807865, 2023). "Subjects with CD36 gene methylation had a significant increase in the DNMT3a level in the control group (p = 0.009) and in the type 2 diabetes group (p = 0.002)." (PMID 36031603, 2022). "For any CHIP, DNMT3A CHIP, TET2 CHIP, and ASXL1 CHIP, the top outcomes reflected CpG sites related to age/aging, alcohol consumption, smoking, and multiple CVD-related traits including body mass index (BMI), type II diabetes, and fasting insulin." (PMID 39070619, 2024). "Moreover, the DNMT3a level was significantly increased in subjects with CD36 gene methylation compared with subjects without CD36 gene methylation in control subjects (p = 0.009) and in subjects with type 2 diabetes (p = 0.002)." (PMID 36031603, 2022). "For example, individuals with type 2 diabetes had higher DNMT3B levels in cultured myotubes and decreased TET1 expression in adipose tissue vs tissue from individuals without type 2 diabetes, while palmitate exposure decreased DNMT3A and DNMT1 expression in human pancreatic islets." (PMID 35307762, 2022).
viral infection (8 papers, 2015 to 2025). "These experiments demonstrate that Dnmt3a-dependent intrinsic programing restricts GC Tfh differentiation during viral infection." (PMID 39677644, 2025). "Considering the possible role of DNMT3A played in viral infection and inflammation, we also detected the relationship between DNMT3A and cardiomyocytes pyroptosis." (PMID 38643118, 2024). "The regulatory role of DNMT3A in viral infection has been discovered through multiple studies." (PMID 38643118, 2024). "Furthermore, DNMT3A is essential in generating type I interferon and providing resistance against viral infection in mice, highlighting its significant role in antiviral immunity." (PMID 38643118, 2024). "Cells under inflammatory stress are expected to produce poor-quality results, especially under stressors such as viral infection and CHIP (typically caused by clones carrying mutations in epigenetic regulators like TET2, DNMT3A and ASXL1), contributing to a lower fraction of high-quality reads." (PMID 37372428, 2023). "Thus, early inhibition of Dnmt3a-mediated de novo methylation using decitabine can enhance the formation of highly functional Tfh cell and memory Tfh cells and may be a strategy to improve the germinal center response to viral infections." (PMID 39677644, 2025). "The results showed that after viral infection, both DNMT1 and DNMT3A displayed a significant increase in expression (P < 0.005)." (PMID 26039376, 2015). "DNMT3A elicited the exhaustion-specific DNA methylation program, and conditional knockout of Dnmt3a in CD8+ effector T cells impacted Tex differentiation state after viral infection." (PMID 36853831, 2023). "Here, we found that DNMT1 rather than DNMT3a or DNMT3b was involved in modification of DNA methylation during H5N1 virus infection; this is because expression of DNMT1 was inhibited upon virus infection, whereas that of the other two DNMTs changed little." (PMID 29717211, 2018).
Infertility (7 papers, 2011 to 2026). "Germline deficiency of DNMT3a, involved predominantly in de novo methylation during gametogenesis, and DNMT3L, an enzyme with no intrinsic methyltransferase activity but that cooperates with DNMT3a in de novo methylation, both result in azoospermia and infertility." (PMID 21949694, 2011).
osteoporosis (7 papers, 2020 to 2025). A condition of reduced bone mass, with decreased cortical thickness and a decrease in the number and size of the trabeculae of cancellous bone (but normal chemical composition), resulting in increased fracture incidence. "Surprisingly, under certain conditions some DNMT3A mutant can cause increased osteoclastogenesis and thus osteoporosis (see under the medical aspects)." (PMID 39819598, 2025). "They found that alendronate, a bisphosphonate commonly used to treat osteoporosis, and IL-20 neutralization reduced osteoclastogenesis and bone loss in Dnmt3a mutant models." (PMID 40080235, 2025). "Animal models have provided further evidence for this association, with Dnmt3a and Tet2 knockout mice showing reduced bone volume and increased osteoclastogenesis, leading to an increased risk of osteoporosis." (PMID 40080235, 2025). "CHIP-related inflammatory signals appear to contribute to remodeling of the bone structure, in particular DNMT3A-mutant CHIP that has been linked to osteoporosis in humans." (PMID 38514772, 2024). "Mouse models of hematopoietic-specific Dnmt3a knockout have also developed osteoporosis, providing additional evidence of DNMT3A’s involvement in the pathogenesis of the disease." (PMID 39819598, 2025). "Our study demonstrated that Nrf2/Dnmt3a/RANKL axis in osteocyte is a new mechanism of osteoporosis." (PMID 38233202, 2024).
anemia (6 papers, 2020 to 2026). A reduction in the number of red blood cells, the amount of hemoglobin, and/or the volume of packed red blood cells. "In a transplant setting, treatment of mice bearing Dnmt3a–/– cells with a PI3Kα/β or PI3Kα/δ inhibitor rescues Dnmt3a mutant–associated hematologic abnormalities, including hepatosplenomegaly, myeloid cell infiltration in the tissues, and anemia as well as thrombocytopenia." (PMID 36976647, 2023). "Previous studies have shown that diseased Dnmt3a–/– mice present with anemia, reduced mature erythroblasts, and an accumulation of immature CD71+Ter119+ proerythroblasts in the spleen and in the BM." (PMID 36976647, 2023). "Anemia was positively correlated with the JAK2 and DNMT3A mutations." (PMID 36139644, 2022).
aortic stenosis (6 papers, 2020 to 2025). Aortic valve stenosis is a aortic valve disease caused by the incomplete opening of the aortic valve. "In human studies, DNMT3A mutations are associated with elevated expression of inflammatory cytokines and T-cell activation, contributing to cardiovascular pathologies like aortic stenosis and heart failure (HF)." (PMID 39997650, 2025). "The study enrolled 279 aortic stenosis patients of which 93 (33%) had mutations in DNMT3A or TET2, the two most common CHIP-driver genes." (PMID 32748835, 2020). "Thus, carrying a DNMT3A- or TET2-CHIP-driver mutation appears to be an independent risk factor for worse clinical outcome in patients with severe aortic stenosis even after removal of the stenotic valve by TAVR." (PMID 36680616, 2023). "Furthermore, in patients with severe aortic stenosis, the presence of DNMT3A mutations has been associated with significantly elevated T helper 17 cell (TH17): regulatory T cells (Tregs) ratio, representing pro-inflammatory T-cell polarisation." (PMID 33861346, 2021). "In a cohort of patients with severe aortic stenosis undergoing transcatheter aortic valve implantation (TAVI), TET2- and DNMT3A-driven CHIP was found to be associated with a profound mortality risk even after successful TAVI." (PMID 39988580, 2025). "Elevated Th17 cells and related cytokines, important in IBD pathogenesis, are similarly observed in DNMT3A-CHIP carriers with severe aortic stenosis." (PMID 39997650, 2025). "In conclusion, carrying a DNMT3A- and/or TET2-CHIP-driver mutation is an independent prognostic risk factor for increased long-term mortality in patients with severe aortic stenosis even after successful removal of the stenotic valve by TAVR." (PMID 36680616, 2023). "While the prevalence of DNMT3A- and/or TET2-CHIP-driver mutations remained similar with 32.7%, the association of CHIP with mortality was even stronger in patients with severe aortic stenosis undergoing TAVR, who never smoked." (PMID 36680616, 2023).
cardiac hypertrophy (6 papers, 2015 to 2025). "Bone marrow-specific deletion of TET2 or DNMT3A is associated with cardiac hypertrophy, fibrosis and impaired LV fractional shortening after infusion of angiotensin II in comparison with WT controls." (PMID 33861346, 2021). "Specifically, DNMT3A−/− engineered human induced pluripotent stem cell-derived cardiomyocytes have up-regulation of pathways involved in cardiac hypertrophy and cardiac proliferation pathways when compared with WT." (PMID 33861346, 2021). "Although mice with DNMT3A deletion in cardiomyocytes showed smaller cardiomyocyte morphology, hypertrophy-related genes were activated again, indicating that the loss of DNMT3A did not lead to the complete disappearance of cardiac hypertrophy." (PMID 38584203, 2024).